RIPK3 (receptor interacting serine/threonine kinase 3)
Diseases named in the same sentence as RIPK3 in open-access papers (continued):
Sharing a sentence is not in itself a finding about the gene and the disease.
tumor (continued). "Taken together, we conclude that pro-necroptic factors such as RIPK1, RIPK3, and MLKL may play a role in supporting tumor growth, and MLKL may be a promising target for cancer treatment." (PMID 26959742, 2016). "However, our in vivo genetic studies showing that double FADD/RIPK3 deficiency did not sensitize mice to AOM-induced colon tumorigenesis provided evidence that regulation of death receptor-induced programmed cell death is not critical for the tumour suppressing role of CYLD." (PMID 27561390, 2016). "Thirteen weeks after AOM-DSS regimen (day 91), lack of RIPK3 promoted marked tumor growth in the middle and distal part of the colon, which closely mirrors the pattern seen in human CRC." (PMID 27344176, 2016). "We detected a similar number of tumour nodules in the lungs of PBS-injected WT and Ripk3−/− mice." (PMID 26381214, 2015). "In addition, the higher expression of RIPK1, RIPK3, and MLKL implicates tumor necroptosis." (PMID 40739587, 2025). "In addition, tumor cells evade necroptosis, a RIPK1/RIPK3/MLKL-dependent death pathway, through downregulation of RIPK3 or MLKL expression, or by exploiting molecular chaperones to suppress pathway activation, enabling escape from TNFα family cytokines or certain chemotherapy-induced cell death." (PMID 41229498, 2025). "Furthermore, ectopic expression of RIPK3 in cancer cells lacking its expression can inhibit tumor growth." (PMID 39949740, 2025). "To address the role of tumor cell necroptosis in cancer immunotherapy with ICI, we used CRISPR-mediated somatic mutagenesis to generate polyclonal tumor cell lines that lack critical components of the necroptotic cell death molecular machinery (RIPK3−/−, MLKL−/−)." (PMID 40345706, 2025). "Moreover, UVB irradiation at a dose of 500 mJ on the dorsal skin of RIPK3 knockout (RIPK3-KO) mice demonstrated a significant mitigation of UVB-induced skin damage, as evidenced by decreased scores of skin damage, as well as ameliorated necrosis and apoptosis of keratinocytes in the mouse epidermis." (PMID 40221399, 2025). "Mice treated with either endothelial cell-specific RIPK3 deletion or receptor-interacting serine/threonine-protein kinase 1 (RIPK1)-inhibitor necrostatin-1 showed a reduction in tumor-cell-induced endothelial necroptosis, tumor cell extravasation, and metastasis." (PMID 39090094, 2024). "By selectively restricting cell death to either RIPK3-dependent apoptosis or necroptosis, we found that immunization with necroptotic cells, but not apoptotic cells showed marked protection to subsequent tumor challenge." (PMID 38196632, 2023). "Therefore, in the context of inflammatory and neoplastic diseases, RIPK3 and MLKL do not necessarily represent the onset of necroptosis, and their roles will need to be assessed in each disease model individually." (PMID 36828808, 2023). "However, RIPK1 and RIPK3, the major components of necrosomes in PC, were upregulated, and cell immunity was induced by C-X-C motif chemokine ligand 1 (CXCL1) and Mincle to promote tumor growth." (PMID 35740953, 2022). "Four out of 14 Ripk3 KO mice did not develop tumours for more than 50 weeks after 3MC treatment." (PMID 35354912, 2022). "Moreover, RIPK1/RIPK3 promote vascular permeability to mediate tumor cells extravasation independent of necroptosis since they allow heat shock protein 27 phosphorylation in lung endothelial cells upon permeability factor treatment (VEGF-A, VEGF-B, FGF-b)." (PMID 33567618, 2021). "Furthermore, the level of RIPK3 and TRIM28 in the tumor could be an indicator for the applicability of ICD-based immunotherapy in the selection for therapeutic approaches." (PMID 34419074, 2021). "However, we observed reduced expression of necroptosis molecules in tumors compared to normal lung tissues, and lower tumor expression of RIPK3 in smokers compared to nonsmokers in this study." (PMID 32742497, 2020).
tumor (continued). "Moreover, the CCR2 KO strain showed no significantly increased tumor proliferation following PH, and the protection observed in RIPK3 KO strain can, at least partially, be attributed to the absence of recruitment of these cells." (PMID 33178579, 2020). "Accordingly, tumor cells lacking RIPK3 were more invasive, both in vitro and in vivo." (PMID 32231206, 2020). "Furthermore, patients with lower expression of RIPK3 or MLKL have worse prognosis for breast cancer or ovarian cancer, respectively, suggesting that resistance to necroptosis is positively selected during tumor growth and/or development." (PMID 30459758, 2018). "Consistent with the B16-F10 tumor model, a decreased number of nodules in the Ripk3−/− mice were found compared with wild-type mice (P=0.14) suggesting the decrease in tumor nodules in the Ripk3−/− was not dependent on the tumor cell type." (PMID 28151480, 2017). "Our results show RIPK3 did not alter tumor growth of established tumors." (PMID 28151480, 2017). "However, the DNA methylation inhibitor 5-Aza-2′-deoxycytidine (5AzadC) and histone deacetylase inhibitor trichostatin A (TSA) did not restore RIPK1 and RIPK3 expression in multiple tumor cell lines." (PMID 25675296, 2015). "Additionally, AAV-induced RIPK3 expression can promote necroptosis in the TME, enhance neoantigen presentation activity, and induce tumor-specific CD8+ T-cell priming, resulting in secondary tumor control and improved therapeutic efficacy of immune checkpoint blockers in various tumor mouse models." (PMID 38799433, 2024). "Moreover, RIPK3-phosphorylated TRIM28 could upregulate NF-κB in tumor cells, leading to elevated immunostimulatory cytokine such as GM-CSF expression, thereby contributing to robust cytotoxic anti-tumor immunity." (PMID 37375731, 2023). "On the contrary, the upregulation of RIPK3 inhibited FAO via the suppression of PPAR activation, and could reverse the immunosuppressive activity of TAMs and dampen HCC tumorigenesis, and inhibition of FAO in TAMs promoted the anti-tumorigenic differentiation of TAMs and inhibited tumor growth." (PMID 34638609, 2021). "Together, these findings support our hypothesis that RIPK3 has anti-tumor properties and that lack of RIPK3 promotes the development of intestinal neoplasia through STAT3- and β-catenin-mediated transcription of angiogenic, mitogenic, tumorigenic and cell cycle regulators." (PMID 27344176, 2016). "Because Ripk3−/− mice exhibited higher tumor burdens accompanied with enhanced production of cytokines and chemokines, we next hypothesized that RIPK3 suppresses tumor development and progression by negatively regulating inflammatory mediators with pro-tumorigenic effects." (PMID 27344176, 2016). "As we observed that during clonogenic and soft agar growth experiments, RIPK3-, RIPK1-, or MLKL- knockout cells tend to have significantly smaller colonies, we hypothesized that the necroptotic genes may regulate important cytokines required for tumor cell growth." (PMID 26959742, 2016). "Thus, one may speculate that HeLa cells were derived from a RIPK3-negative adenocarcinoma or a negative part of a tumor with heterogeneous RIPK3 expression." (PMID 25888634, 2015). "Regardless of the expression of RIPK3 and MLKL, tumor cells showed necrotic morphological characteristics when treated with NB under US irradiation, suggesting that the occurrence of cell necroptosis was independent of RIPK3/MLKL." (PMID 37984863, 2024). "Another study demonstrated reduced or absent expression of RIPK3 in human AML primary samples without variations in RIPK1, highlighting the potential of tumor cells to escape necroptosis to survive." (PMID 38730609, 2024). "Consistent with our findings with tumor lysates, the levels of ZBP1 and RIPK3, but not RIPK1, are dramatically increased in GFP-MVT-1 cells isolated from tumors compared to that in cultured cells." (PMID 33976222, 2021).
tumor (continued). "Previous reports studied the possible involvement of necroptosis in tumor development and metastasis, using RIPK1 or RIPK3 KO cells/mice without directly examining tumor necroptosis." (PMID 33976222, 2021). "Transient events such as phosphorylation of RIPK3 and MLKL are not easily detectable in the context of human or murine tumor models." (PMID 32231206, 2020). "Similarly, in breast cancer models, the absence of RIPK1, RIPK3, and MLKL results in slower tumor growth and heightened sensitivity to radiotherapy." (PMID 39949740, 2025). "Regardless of the RIPK3 status in tumor cells, using optogenetically activatable MLKL can still trigger the release of both cDAMPs and iDAMPs, demonstrating its ability to elicit an immune response independent of upstream RIPK3 signaling." (PMID 39921454, 2025). "Due to the low percentage of cases with tumor cells with positive immunoreaction for RIPK3, the ROC and AUC for this marker have not been calculated, while for AXL, an exploratory cutoff of 27.5% of positive tumor cells has been calculated with the Youden criteria." (PMID 34745951, 2021). "Further studies focused in investigating the role of necroptosis in gliomagenesis and tumor progression will elucidate whether MLKL and RIPK3 are not only relevant LGG prognostic biomarkers but also potential targets for therapeutic intervention, as they constitute the core machinery of necroptosis." (PMID 37651429, 2023). "However, taking advantage of the fact that concomitant deletion of RIPK3 fully prevents skin lesion formation in mice with keratinocyte-restricted FADD knockout (FADDE-KO), we generated Sharpincpdm/cpdm;Ripk3−/− mice that also lacked FADD specifically in keratinocytes." (PMID 25443631, 2014).
cancer (172 papers, 2015 to 2026). A tumor composed of atypical neoplastic, often pleomorphic cells that invade other tissues. "There are still many unsolved questions: does MLKL cleavage occur in other RIPK3-deficient cancer cells and is the C-terminal cleavage ubiquitinated and degraded by proteasome after cleavage." (PMID 35965541, 2022). "Naked mole rats are found to be resistant to cancer development through dampened inflammatory response due to genetically determined impaired necroptosis, with essential necroptosis genes RIPK3 and MLKL containing mutations causing premature stop codons." (PMID 35354912, 2022). "A necroptosis sensitivity screening revealed that 780 (83%) cell lines among a panel of 941 human cancer cell lines from 28 tissues are fully resistant to necroptosis due to the loss of RIPK3 expression that mediated by oncogenes BRAF and AXL." (PMID 39872161, 2022). "Accordingly, changes in RIPK3 expression have been associated with a range of inflammatory diseases and cancers." (PMID 34153072, 2021). "The loss of key necroptotic proteins, particularly RIPK3, has been reported in multiple cancer cell lines and primary tissues." (PMID 31914150, 2020). "RIPK3 expression is absent or decreased in numerous cancer cell lines; specifically, the loss of RIPK3 protein expression was found in two-thirds of the 60+ cancer cell lines tested." (PMID 31122251, 2019). "We show that BRAF and AXL oncogene overactivation in cancers is likely to be among the driving forces for the loss of RIPK3 during tumorigenesis and the consequent escape from necroptosis, as well as other RIPK3-driven processes." (PMID 30157175, 2018). "The loss of RIPK3 is a heterogeneous event, and its extent differs across various cancer cases, as can be seen from the screen data and the xenograft data." (PMID 30157175, 2018). "We discover BRAF and AXL as the first two oncogenes that can drive the loss of RIPK3 expression in cancer cells." (PMID 30157175, 2018). "Having established that RIPK3 expression loss is observed during tumorigenesis and that this loss is prevalent across cancer types, we next set out to identify drivers of this loss." (PMID 30157175, 2018). "Our results reveal a potential role of BRAF and AXL oncogenes in driving the loss of RIPK3 expression and escape from necroptosis in various cancers." (PMID 30157175, 2018). "In this study, we performed a necroptosis sensitivity screen in 941 human cancer cell lines to identify the mutational drivers of the RIPK3 expression loss and the consequent escape from necroptosis." (PMID 30157175, 2018). "Low RIPK3 expression is associated with a reduced OS in patients with colorectal and breast cancer." (PMID 38213773, 2024). "Notably, the resistance of cancer cells to necroptosis is driven by certain oncogenes associated with the loss of RIPK3, such as BRAF and AXL." (PMID 38684668, 2024). "Therefore, it is a better choice for patients with RIPK3-deficient cancers to receive hypomethylating agents to induce RIPK3 expression before receiving conventional chemotherapeutics." (PMID 38553639, 2024). "Moreover, at least in the metastatic T-47D cancer line, the DS variants also increased the expression of RIPK3 via the pathways that require the activity of the small Rho GTP-ases and that are also regulated by NFκB." (PMID 39062543, 2024). "From these findings, an alternative necroptotic pathway may be inferred in RIPK3-deficient cancer cells, for example in MM cells, where necroptosis may be executed by N-terminal cleavage of MLKL when caspases are activated." (PMID 35965541, 2022). "Collectively, this present study suggests that caspase-mediated necroptosis may occur under (patho)physiological conditions, delineating a novel regulatory mechanism of necroptosis in RIPK3-deficient cancer cells." (PMID 35965541, 2022). "Escape from necroptosis via loss of RIPK3 expression is a feature of some cancers." (PMID 33194736, 2020).
cancer (continued). "Overall, these findings suggest that AXL/TYRO3 overexpression, frequently seen in cancers, promotes the loss of RIPK3 expression and escape from necroptosis, which may be reversed upon inhibition of these kinases." (PMID 30157175, 2018). "Various cancer types loose expression of Ripk3 and/or acquire Caspase-8-inactivating mutations." (PMID 29867129, 2018). "In order to identify the mechanisms driving RIPK3 expression loss in cancer cells, we performed a necroptosis sensitivity screen using a panel of 941 human cancer cell lines from the Genomics of Drug Sensitivity in Cancer (GDSC) collection, which represent various cancer types from 28 tissues." (PMID 30157175, 2018). "Moreover, high AXL/TYRO3 levels are potential predictors/biomarkers for loss of RIPK3 expression and necroptosis resistance in cancer." (PMID 30157175, 2018). "Moreover, BRAF overactivating mutations are potential predictors/biomarkers for loss of RIPK3 expression and necroptosis resistance in cancer." (PMID 30157175, 2018). "In addition to increased methylation, a loss of expression of RIPK3 in cancer cell lines could be detected in further data sets." (PMID 38397165, 2024). "The loss of Receptor-interacting serine/threonine-protein kinase 3 (RIPK3) expression and necroptotic potential have been previously reported in several cancer cell lines; however, the extent of this loss across cancer types, as well as its mutational drivers, were unknown." (PMID 30157175, 2018). "RIPK3 plays important roles in cancer and likely cancer therapy, in part by killing cancer cells, repressing their growth, and/or promoting efficient anticancer responses by the immune system." (PMID 40010643, 2025). "For instance, key necroptotic proteins, such as RIPK3, are often downregulated in various cancers, and patients with low RIPK3 expression generally have poorer prognosis compared to those with higher expression." (PMID 39949740, 2025). "In particular, CASP8 and NLRP3 were hypomethylated in many cancers, whereas RIPK3 was hypermethylated." (PMID 38436818, 2025). "Understanding the roles of RIPK3 and necroptosis is critical to being able to modulate possible therapeutics for cancer and inflammatory diseases." (PMID 40010643, 2025). "We further assessed the protein levels of SPOP, RIPK1, and RIPK3 in representative cell lines of 5 cancer types." (PMID 41122967, 2025). "RIPK3 has been shown to activate and regulate the necroptosis programmed cell death pathway in OS and other cancers." (PMID 40332549, 2025). "Quantitative mass spectrometry analysis in combination with functional genomics data revealed lower numbers of RIPK3 compared to RIPK1 in the majority of cancer cells." (PMID 40240880, 2025). "RIPK3, a key component of the necrosome, is frequently silenced via methylation in various cancer cell lines." (PMID 38727208, 2024). "On the one hand, RIPK3 inhibits cancer development by directly killing cancer cells through necroptosis." (PMID 38684668, 2024). "Given that RIPK3 can be targeted to inhibit the accumulation of MAIT cells, targeting RIPK3 can be combined with chemotherapy for the treatment of cancer." (PMID 38684668, 2024). "Since the evasion of cell death is considered one of the characteristic abilities of malignant tumors, RIPK3 has already been investigated in relation to tumorigenesis." (PMID 38397165, 2024). "Our study highlights the dual role of the RIPK3-driven necroptotic system in improving the safety and efficacy of cancer cell–based therapy, with broader implications for cellular therapies." (PMID 39560995, 2024). "Preventive immunization (gold standard vaccination assay) of mice with necroptotic cancer cells induced by ectopic RIPK3 expression can induce antitumor immunity." (PMID 38799433, 2024). "MLKL and RIPK3 are vital for the induction of necroptosis and are known to be suppressed or altered in many cancers." (PMID 38893185, 2024).